IGHV3OR16-10 (immunoglobulin heavy variable 3/OR16-10 (non-functional))
Synonyms: IGHV3/OR16-10
Gene: Immunoglobulin variable (V) gene on chromosome 16 (32,995,048 to 32,995,505, forward strand). Ensembl gene ENSG00000233732.
Gene Ontology:
Molecular function: antigen binding
Biological process: immunoglobulin mediated immune response
Cellular component: extracellular region; plasma membrane
Homologues: Orthologues: macaque IGHV3OR16-10 (76% identical). Paralogues in human: IGHV3-23 (89% identical), IGHV3-64 (89% identical), IGHV3-74 (88% identical), IGHV3-13 (86% identical), IGHV3-48 (86% identical), IGHV3OR16-13 (86% identical), IGHV3-21 (85% identical), IGHV3-64D (85% identical), IGHV3-66 (85% identical), IGHV3-7 (85% identical), IGHV3-11 (84% identical), IGHV3-20 (84% identical), and 65 more.